ZNF234 (zinc finger protein 234)
Description:
May be involved in transcriptional regulation.
Synonyms: ZNF269; HZF4
Tractability: PROTAC: ubiquitination databases record sites on it.
Gene: Protein-coding gene on chromosome 19 (44,141,355 to 44,160,313, forward strand). Ensembl gene ENSG00000263002.
Subcellular location: Nucleus
Subcellular location (Human Protein Atlas): Nuclear bodies
Pathways (Reactome):
Gene expression (Transcription): Generic Transcription Pathway
Gene Ontology:
Molecular function: DNA-binding transcription factor activity; sequence-specific DNA binding
Biological process: negative regulation of transcription by RNA polymerase II; regulation of DNA-templated transcription
Cellular component: nucleoplasm; nucleus
Genetic constraint (gnomAD): Loss-of-function variants: 5 observed, 8.27 expected, observed/expected ratio (o/e) 0.6, 90% interval 0.31 to 1.27. That is too few expected variants to judge how well the gene tolerates losing a copy. Missense variants: 709 observed, 862.83 expected, observed/expected ratio (o/e) 0.82, 90% interval 0.77 to 0.87. Synonymous variants: 258 observed, 292.25 expected, observed/expected ratio (o/e) 0.88, 90% interval 0.8 to 0.98.
Homologues: Orthologues: chimpanzee ZNF234 (99% identical). Paralogues in human: ZNF226 (75% identical), ZNF112 (48% identical), ZNF45 (46% identical), ZNF229 (44% identical), ZNF235 (43% identical), ZNF227 (43% identical), ZNF33B (41% identical), ZNF658 (41% identical), ZNF28 (41% identical), ZNF726 (41% identical), ZNF606 (40% identical), ZNF568 (40% identical), and 164 more.
Diseases named in the same sentence as ZNF234 in open-access papers:
ZNF234 is named in the same sentence as 6 diseases in open-access papers, as found by Europe PMC text mining. Sharing a sentence is not in itself a finding about the gene and the disease. The quoted sentences say what the papers report.
migraine (1 paper, 2023). "A larger study of epigenetic changes in SH2D5, NPTX2, COMT, GIT2, ZNF234, and SOCS1 genes is necessary to understand the processes of migraine chronicity and MOH development." (PMID 37298078, 2023). "One study showed that methylation of some CpG sites of COMT, GIT2, ZNF234, and SOCS1 genes could be important for drug addiction and transformation of migraine into MOH, but studies on larger patient cohorts are needed to fully explore this issue." (PMID 37298078, 2023).
ZNF234 also shares sentences with these, for which no sentence is quoted: psychosis (2 papers); cerebellar degeneration (1); ovarian teratoma (1); small cell lung carcinoma (1); tumor (1).